IL1B (interleukin 1 beta)
Diseases named in the same sentence as IL1B in open-access papers (continued):
Sharing a sentence is not in itself a finding about the gene and the disease.
depression (continued). "Studies report that the plasma levels of proinflammatory cytokines such as interleukin-1β (IL-1β), IL-6, IL-12, CC chemokine Ligand (CCL-2), Tumor Necrosis Factor (TNF)-α, prostaglandin E2 are increased in patients suffering from depression." (PMID 38473935, 2024). "The intervention of Astragalus polysaccharide (APS) significantly reduced the levels of hippocampal TNF-α, IL-1β, and IL-6 in rats with CUS-induced depression." (PMID 38389919, 2024). "IL-10 expression was inhibited in the CUMS model, and increased levels of IL-1β, IL-6, and TNF-α were observed in the sera of the CUMS mice with depression-like behaviors." (PMID 38378622, 2024). "Activation of GPR55 using O-1602 inhibited the activation of the inflammasome, normalizing the increased expression of IL-1β (IL-6 and TNF) and the decreased expression of IL-4 and IL-10, respectively reducing the depression- and anxiety-like behavior." (PMID 38796643, 2024). "P2X7R inhibition or deficiency prevented NLRP3 inflammasome activation and the production of IL-1β, suggesting a potential mechanism for P2X7R in mediating atrial remodelling in depression." (PMID 38261756, 2024). "On the contrary, the elevated serum levels of IL-1β, IL-6, and TNF-α have been repeatedly observed in major depressive disorder and in bipolar disorder." (PMID 33902760, 2023). "Inflammatory cytokines, such as IL-1β, TNF- α and IL-6 but also HPA axis imbalanced regulation of glucocorticoids, are mainly present in depression and anxiety patients." (PMID 37764111, 2023). "rTMS at 10 Hz to the left DLPFC can reduce the serum levels of IL-1β and TNF-α in elderly patients with refractory depression, and this change correlates with Hamilton Depression Rating Scale (HDRS) scores." (PMID 36624089, 2023). "In contrast, in a model of depression induced by tumor necrosis factor alpha (TNF‐α), IL‐1β expression in the hippocampus and reduced neurogenesis in dentate gyrus were observed." (PMID 37031383, 2023). "Levels of proinflammatory cytokines in peripheral blood were shown to be significantly increased in patients with major depressive disorder, such as IL-6, TNF-α and IL-1β." (PMID 37808199, 2023). "The patients showed a significant increase in the levels of inflammatory markers IL-1β (p < 0.001), TNF-α (p < 0.001), and CRP (p < 0.001), despite improvement in PTSD (p < 0.001) and depression (p < 0.001) symptoms from baseline through one year follow-up." (PMID 37081449, 2023). "Several studies have shown that the intraperitoneal injection of LPS upregulates the expression of proinflammatory cytokines, including IL-1β, IL-6, and TNF-α, leading to anxiety, depression, and cognitive deficits." (PMID 37560531, 2023). "For example, long-term corticosterone treatment significantly increased the mRNA levels of IL-1β, IL-6, and TNF-α in the hippocampus and hypothalamus, which in turn increased the anxiety-and depression-like behaviors in mice." (PMID 37168717, 2023). "The onset of “leaky gut” can trigger an inflammatory response, resulting in symptoms such as lethargy, depression, anorexia, and social withdrawal through the modulation of pro-inflammatory cytokines (TNF-a, IL-6, IL-1B)^142." (PMID 37375546, 2023). "Researchers have proven that intestinal barrier destruction in depression is related to an increase in proinflammatory factors like LPS and TNF-α and IL-1β." (PMID 37025378, 2023). "An increase in pro-inflammatory cytokines, namely IL-6, IL-1β, tumor necrosis factor α, and C-reactive protein (CRP), participate actively in the development of depression." (PMID 37139495, 2023).
depression (continued). "Several groups including ours have identified the roles of inflammation-related molecules, such as IL-1β, TNF-α, and PGE2, for depression-related behaviors in a mouse model of chronic stress, which has often been used to study depression." (PMID 37443823, 2023). "Cytokines such as IL-1β, IL-6, TNF-α, and IFN-γ are known for their importance in depression mechanisms." (PMID 37834806, 2023). "And a large number of studies have shown that depressed patients with depression have C-reactive protein (CRP), prostaglandins, and other arachidonic acid derivatives, as well as IL-6, IL-1β and TNF-α were significantly increased." (PMID 37492068, 2023). "The biological link between depression and CVD may be related to the overactivation of the hypothalamic−pituitary−adrenal axis results in the dysregulation of immune system and further causes high levels of proinflammatory cytokines (such as IL‐1β, TNF‐α, and IL‐6) released by macrophages." (PMID 37593998, 2023). "Ketamine, a novel rapid-acting antidepressant, reduces serum and cerebrospinal fluid IL-6, and serum IL-1β and TNF-α, while treating depression." (PMID 36838809, 2023). "Our present results showed that long-term EE effectively decreased the expression levels of IL-1β, IL-6, and TNF-α, and improved depression and cognitive deficits in the MSD + EE group compared with those of the MSD group." (PMID 37168717, 2023). "Simvastatin (20 mg/kg) has been shown in animal tests to diminish depression-like behaviour by lowering hippocampal inflammatory cytokines such as TNFA, IL1B and IL6, hence alleviating lipopolysaccharide-mediated depression and inflammation induced stress." (PMID 36602642, 2023). "Compared with healthy controls, the plasma levels of mBDNF, tPA, and IL-1β were higher in MDD patients, which indicates that inflammation is involved in the pathogenesis of depression." (PMID 37626579, 2023). "It is well known that activated microglia release pro-inflammatory mediators and oxidative products such as IL-1β, TNF-α, and MDA, which promote neuronal damage and induce the development of depression." (PMID 36793870, 2023). "Serum level analysis of cortisol, DHEA, TNF-α, IL-6, IL1β in 12 women with BPD and depression (age: 25.6 (3.9)), compared to 12 healthy women (age: 26.3 (5.1))." (PMID 36946840, 2023). "Some cytokines, such as IL-1β, IL-6 and tumour necrosis factor-α (TNF-α) appear to be involved in the onset and progression of depression." (PMID 37836393, 2023). "Patients with major depression have been repeatedly observed to have activated inflammatory pathways, as manifested by increased proinflammatory cytokines such as TNF-α and IL-1β." (PMID 38259687, 2023). "IL-1β- or TNF-α-knockout mice show reduced levels of anxiety, depression, and cognitive decline relative to that seen in their wild-type counterparts." (PMID 37560531, 2023). "Elevated levels of neuroinflammatory cytokines such as interleukin (IL)-1β, tumor necrosis factor-α (TNF-alpha) and IL-6 have been identified in patients with depression." (PMID 36829840, 2023). "Some inflammatory markers interact with early life stress and can predict depression, such as TNF-α and IL-1β." (PMID 37700748, 2023). "GP-14 treatment effectively inhibited the increase of pro-inflammatory cytokines, for example, IL-6, IL-1β, and TNF-α, in the serum from mice in the LPS-induced depression model." (PMID 37631068, 2023). "In the rat of CUMS model, rTMS treatment significantly improved anxiety and depression-like behavior and reduced the levels of inflammatory factors TNF-α, iNOS, IL-1β, and IL-6 in the hippocampus." (PMID 36624089, 2023). "Elevated levels of inflammatory markers such as IL-1β, IL-6, IL-2, TNF-α, CRP and PGE2 were found in patients with depression." (PMID 37387537, 2023). "Proinflammatory cytokines, involving TNFα, IL1β, IL6, and interferon, are important regulators in the pathogenesis of depressive disorder." (PMID 38273824, 2023).
depression (continued). "Numerous evidence suggests that proinflammatory cytokines, such as interleukin (IL)-6, IL-1β, and tumor necrosis factor alpha (TNF-α), are elevated in individuals with depressive disorder." (PMID 37600668, 2023). "High concentrations of IL-1β and TNF-α have recently been observed to be related to the early onset of depressive disorder." (PMID 37834806, 2023). "As was revealed in several experiments in animal models of depression, quercetin exerted antioxidant (reducing ROS, increasing SOD, GST, GSH activity) as well as anti-inflammatory activity (suppressing IL-1β, IL-6, TNF-α, COX-2, microglial activation)." (PMID 35455082, 2022). "Increase in inflammatory cytokines (IL-1β, IL-6, and TNF-α) has also be reported in common neuropsychiatric conditions including depression and schizophrenia." (PMID 35538558, 2022). "In similar studies, patients with depression were found to have elevated levels of proinflammatory cytokines, including tumor necrosis factor-α (TNF-α), interleukin 1β (IL-1β), IL-6, and C-reactive protein (CRP)." (PMID 35054853, 2022). "The levels of IL-4, IL-10, T, and NPY in depression patients, DCMI patients, and CUMS + LPS model rats elevated, while the levels of IL-1β, IL-6, and TNF-α were reduced." (PMID 35432561, 2022). "That is, the greater the depression is, the higher the levels of anxiety and cortisol and the lower the levels of IFN‐γ, IL‐1β, and IL‐12." (PMID 35588458, 2022). "It has been shown that the inflammatory factors IL-1β, IL-6, TNF, and C-reactive protein (CRP) in peripheral blood are reliable biomarkers for patients with depression." (PMID 36186850, 2022). "Researchers have observed high levels of pro-inflammatory cytokines including interleukin-1β (IL-1β), IL-6, and tumor necrosis factor-α (TNF-α) in the blood of patients suffering from depression and anxiety." (PMID 35242039, 2022). "The biomarkers assessed in the studies involving depression include IL-6 (n = 5), IL-10 (n = 4), TNF-α (n = 4), IL-1β (n = 2), CRP (n = 2), and IL-7 (n = 1)." (PMID 35053845, 2022). "In an 8-week CMS-induced depression paradigm, C57BL/6 mice exhibited an increase in the number of Iba-1 positive cells and levels of IL-1β, IL-6, and TNF-α." (PMID 35668399, 2022). "Antidepressants decreased IL-1β and IL-18 levels in serum and suppressed NLRP3 expression in MDD patients and mice with stress-induced depression." (PMID 36558541, 2022). "Prior evidence suggests that inflammatory cytokines (such as IL‐1β, IL‐6, and TNF‐α) are related to anxiety and depression in cancers, including colorectal cancer, breast cancer, and pancreatic cancer." (PMID 34697903, 2022). "Classical monocytes lead to ischemic lesions by producing IL-1β, IL-6, and TNF-α, which are connected with the presence of depression." (PMID 35935403, 2022). "In fact, the downstream cytokines of NLRP3, including IL-1β and TNF-α, were increased in the cerebral spinal fluid and serum of patients with depression." (PMID 36187801, 2022). "Furthermore, high TNF-α (P=0.044, P=0.176 after adjustment), high IL-1β (P=0.012, P=0.048 after adjustment), increased IL-6 (P=0.010, P=0.040 after adjustment), and increased IL-17 (P=0.010, P=0.040 after adjustment) were correlated with increased depression severity grade." (PMID 35239774, 2022). "Studies have shown that Rg1 reduced the levels of IL-1β, TNF-α, caspase-1, IL-2, IL-6 and IL-18 via the suppression of Connexin43 (Cx43) ubiquitination in depression." (PMID 36010610, 2022). "The AGE-RAGE signaling pathway mediates NF-kB activation and upregulates the expression of proinflammatory cytokines (e.g., IL-1β, IL-6 and TNFα) and growth factors (e.g., VEGF), which contribute to depression development and progression." (PMID 35626632, 2022). "The concentrations of depression-related factors (5-HT and DA) and inflammatory factors (TNF-α, IL-6, and IL-1β) in the hippocampus and serum were assessed by ELISA assay." (PMID 36506556, 2022).
depression (continued). "Meta-analyses and systematic reviews show that levels of IL-1β, IL-2, IL-4, IL-8, the soluble IL-6 receptor (sIL-6R), IL-5, CCL3, IL-17A, and TGF-β1 are significantly changed in depression." (PMID 36614020, 2022). "The therapeutic effect of PAP on depression-like behaviors and its regulatory role on protein expressions of NF-κB, NLRP3, ASC, Caspase-1, GSDMD-N, Cleaved-IL-1β, and Cleaved-IL-18, etc., paved the way for us to understand PAP and its effect on pyroptosis." (PMID 35401226, 2022). "IDO1, a therapeutic target in depression, metabolizes tryptophan to KYN and is upregulated during pro-inflammatory states induced by several cytokines (IL-1β, IL-6, IFN-α, TNF-α)." (PMID 35501309, 2022). "Patients with both depression and IPD presented with increased levels of cortisol and IL-1β in another study." (PMID 35330865, 2022). "Here, in a mouse model of depression, FPF ameliorated SD stress-induced depression-like behavior, reducing SD-stress-elevated plasma ACTH and corticosterone levels and TNF-α and IL-1β mRNA expression." (PMID 36614066, 2022). "Furthermore, some pro‐inflammatory cytokines (IL‐12, IFN‐γ, and IL‐1β), but not all, are involved in the regulation of anxiety in patients with PD and are negatively associated with greater severity of depression, GI symptoms, bodily pain, and poorer physical health." (PMID 35588458, 2022). "The levels of neuropeptide Y (NPY), testosterone (T), and IL-1β, IL-6, TNF-α, IL-10, and IL-4 in the peripheral blood plasma of normal people, patients with depression, and patients with DCMI were measured." (PMID 35432561, 2022). "FA and serum cytokines (IL-1β, IL-6, TNF-α, and IFN-γ) were measured in 25 patients with depression (DE) and 24 healthy controls (HC)." (PMID 36261698, 2022). "It has recently been reported that patients with major depressive disorder have higher levels of NLRP3, caspase-1, and IL-1β in serum or peripheral blood mononuclear cells." (PMID 36339940, 2022). "Elevated IL-1β, IL-6, TNF-α and IL-17 levels were observed in clinical patients with pain and depression comorbidity." (PMID 35733107, 2022). "The M1 state of microglia is characterized by the elevated secretion of proinflammatory cytokines, including IL-1β, IL-6, and TNF-α, which trigger neuronal damage and contribute to the development of anxiety and depression." (PMID 35209199, 2022). "For instance, in colorectal cancer patients, serum IL‐1β, IL‐6, interleukin‐8 (IL‐8), and TNF‐α are positively correlated with increased anxiety and depression." (PMID 34697903, 2022). "In CUMS-induced rat model of depression, icariin produces anti-neuroinflammatory and anti-depression effect partially by the inhibition of NF-ĸB pathway and the NLRP3-inflammasome/caspase-1/IL-1β axis." (PMID 35165207, 2022). "A study on the role of neurodevelopment and genes in psychiatric comorbidity and the regulation of inflammatory process in AD revealed that St8sia2 was only associated with the existence of clinical depression, rather than with AD, and St8sia2 could regulate inflammatory factors (IL-6, IL-1β, etc.)." (PMID 36279395, 2022). "COX-2 inhibition has also been shown to influence IL-1β, TNFα, and PGE, and thereby modulate clinical symptoms of depression." (PMID 35415080, 2022). "Compared with healthy controls, patients with major depression have exhibit increased TNF-α and IL-1β levels both in the cerebrospinal fluid and in the peripheral blood circulation." (PMID 36052143, 2022). "In the current study, eight weeks supplementation with vitamin D was not able to significantly change serum concentrations of pro-inflammatory biomarkers including IL-1β, IL-6 and hs-CRP in the subjects with mild to moderate depression." (PMID 36368945, 2022). "Enormous studies have manifested increased levels of proinflammatory cytokines such as CRP, IL-1β, IL-6, and TNF-α in elderly patients with depression (and the patients underwent surgery)." (PMID 35356751, 2022).
depression (continued). "In particular, IL-1β, IL-2, IL-6, TNF-α and IFN-γ are reported to be involved in cytokine-induced depression." (PMID 36045388, 2022). "Furthermore, TNF‐α, IL‐1β, IL‐6, and IL‐17 were all positively associated with HADS‐A score (all P < 0.05), anxiety occurrence (all P < 0.05), HADS‐D score (all P < 0.05), and depression occurrence (all P < 0.05) in NSCLC survivors, while the correlation‐coefficients were weak." (PMID 34697903, 2022). "Not only pro-inflammatory cytokines (e.g., IL-1β and TNF-α) were found to be dysregulated in depression patients, but also IL-1β, IL-6, TNF-α, or lipopolysaccharide (LPS) administration in animal models led to depression- and anxiety-like behaviours." (PMID 36145259, 2022). "Clinical evidence showed that inflammatory mediators were elevated in patients with depressive disorder, such as HMGB1, IL‐1β, TNF‐α, CRP, IL‐6, and so on." (PMID 35089644, 2022). "NE acts on microglia and regulates the release of inflammatory factors such as interleukin 6 (IL‐6), interleukin 1β (IL‐1β), and tumor necrosis factor α (TNF‐α); therefore, NE regulates neuroinflammation, neuropathic pain, anxiety, and depression." (PMID 37786561, 2021). "The colon levels of IL-6, IL-1β, and TNF-α in the depression model group was significantly increased (p < 0.01; F = 19.265, F = 38.3, and F = 57.968, respectively) compared with the control group." (PMID 33505499, 2021). "Following identification of elevated IL-1β, IL-6, and TNF-α levels in the pathophysiology of major depressive disorder, the interaction of BHB with NLRP3 inflammasome was probed in a relevant murine model of this disorder." (PMID 34443594, 2021). "Demonstrated in some studies is the long-lasting increased level of such cytokines as, for example, IL-6, IL-1β and TNF-α, which means a longer exposure to factors contributing to the development of depression." (PMID 34575258, 2021). "The IL-1β, IL-6, and TNF-α proinflammatory cytokines were previously reported as elevated in patients with depression and appear to play significant roles in the pathogenesis of major depression." (PMID 34209804, 2021). "We also examined the effect of CSDS on PFC microglial cytokine expression, including IL‐1β, TNF‐α, and IL‐6, as those are reportedly increased in the cerebrospinal fluid and/or peripheral blood of patients with depression." (PMID 34043886, 2021). "The pro-inflammatory cytokines such as interleukin-6 (IL-6), interleukin-1β (IL-1β), and tumor necrosis factor-α (TNF-α) in peripheral and central nervous system are significantly increased in patients with depression." (PMID 34772918, 2021). "UCMS induced anhedonia and hopeless behavior in mice, and changed expression levels of the depression-related genes BDNF, CREB, GR, SGK1, FKBP5, IL-1β, IL-6, and TNF-α in the frontal cortex and hippocampus." (PMID 34358084, 2021). "The levels of interleukin-1 beta (IL-1β), interleukin-6 (IL-6), and tumor necrosis factor alpha (TNF-α) in the serum of patients with depression are also significantly higher than those of normal people." (PMID 33790789, 2021). "Research showed that in the LPS-induced depression murine model, following LPS treatment for 24 h, NLRP3 brain inflammation, ASC and caspase 1 and IL-1β mRNA protein levels increased significantly." (PMID 34526897, 2021). "Si-Ni-San reduces the release of inflammatory factors IL-1β, IL-6, IL-2, and TNF-α in the peripheral fluid of patients with post-stroke depression and regulates the over-activation of the HPA axis, thereby exerting an antidepressant effect." (PMID 33790789, 2021). "A variety of proinflammatory cytokines such as IL-1β, IL-6, TNF, and Toll-like receptor 3 (TLR3) has been found to overexpress depression." (PMID 34650925, 2021). "There is now ample evidence that the levels of pro-inflammatory cytokines (IL-1β, IL-6, or TNF-α) are elevated in depressed patients and animal models of depression." (PMID 35011254, 2021).